TLR4 (toll like receptor 4)
Diseases named in the same sentence as TLR4 in open-access papers (continued):
Sharing a sentence is not in itself a finding about the gene and the disease.
tumor (continued). "To verify whether autophagosome formation was increased in cachectic muscle of LLC tumor-bearing mice in a TLR4-dependent manner, we overexpressed GFP-LC3 in mouse TA and observed increased GFP-LC3-labeled autophagosomes in LLC tumor-bearing WT but not TLR4−/− mice." (PMID 28536426, 2017). "Two weeks after the final injection of the TLR4/9 agonist complex, the expression of activated caspase-3 and PCNA in the lung tissue of the mice treated with the immune complex was similar to that in the mice treated with PBS in the absence of tumor cell inoculation." (PMID 21931823, 2011). "Consistent with their roles in immune surveillance, TLR4 and TLR8 are expressed in non-malignant and malignant cells, especially in tissues exposed to the external environmental, such as lung and the gastrointestinal tract, where may influence the tumor cell survival and the resistance to apoptosis." (PMID 40025339, 2025). "However, the expression levels of HMGB1 vary in different tumor types and evolve along with tumor progression, implying that some malignant cells may express HMGB1 to levels that are not compatible with the activation of TLR4 and RAGE in immune cells upon release." (PMID 25964783, 2015).
infection (1,499 papers, 2005 to 2026). The state of being infected such as from the introduction of a foreign agent such as serum, vaccine, antigenic substance or organism. "Although 3d mice survived longer than MyD88-deficient mice, they ultimately succumbed early during the infection, showing similar susceptibility to K. pneumoniae as TLR4-deficient mice." (PMID 40248691, 2025). "The goal of our study was to evaluate if low tlr4 responsiveness to leptospiral LPS in C3H-HeJ mice is the factor that drives susceptibility to infection with pathogenic Leptospira." (PMID 39975062, 2025). "Specifically, patients carrying the TLR4 rs4986790 mutation were more likely to develop severe infections and had significantly longer hospital stays." (PMID 40692949, 2025). "We found that the C3H-HeJ mouse was the only strain that sustained lethal infection, thus confirming the association between tlr4 function and acute disease." (PMID 39975062, 2025). "Clinical experience with anti-inflammatory biologics and TLR4 inhibitors demonstrates increased infection risk, unpredictable immune suppression, or unpredictable inflammatory rebounds." (PMID 41373468, 2025). "Numerous studies have revealed a connection between TLR4 polymorphisms and susceptibility to infections." (PMID 41295183, 2025). "The upregulation of tissue protective pathways, including enhanced endothelial development and wound healing mechanisms, suggests that TLR4 deficiency allows the host to better tolerate infection-associated damage." (PMID 40821830, 2025). "TLR4 deficiency markedly reduced the early (3 h post-infection) HMPV-induced TNF mRNA expression, whereas HMPV-stimulated IFNB1 mRNA expression was unaffected." (PMID 41346628, 2025). "C3H-HeJ was the only strain that sustained lethal infection thus confirming an association between a fully functional tlr4 gene and susceptibility to acute L. interrogans infection." (PMID 39975062, 2025). "Bacterial pathogen-associated molecular patterns activate the Tlr2/Tlr4–Myd88 pathway in pathological environments, converting infection signals into bone resorption signals, activating RANKL expression and inducing bone destruction." (PMID 40307566, 2025). "Patients carrying the TLR4 rs4986790 mutation were more likely to develop severe infections (OR = 2.5, 95% CI: 1.8–3.5, p < 0.01) and had significantly longer hospital stays (HR = 1.8, p < 0.05)." (PMID 40692949, 2025). "Infections with wild-type or ΔmsbB strains in TLR4- or caspase-11-deficient mice led to similar mortality rates and partial reduction in cytokine profiles." (PMID 41304196, 2025). "This review examines the literature on the impact of specific polymorphisms in TLR2 and TLR4 on fungal recognition and infection." (PMID 41295183, 2025). "TLR4 gene polymorphisms (e.g., D299G) can blunt responses to LPS and are associated with increased infection risk." (PMID 41568029, 2025). "In fact, numerous studies have identified links between tlr4 polymorphisms and infection outcomes from A. baumannii pneumonia in humans." (PMID 40817088, 2025). "Double knockout mice (DKO)(TLR2-/-,TLR4-/-) were very susceptible to infection, while all the wild-type mice(WT) and TLR2 -/- mice survived." (PMID 39729468, 2024). "Bacterial LPS, a type of the pathogen-associated molecular patterns (PAMPs) agonist of the TLR4 Toll-like receptor, was used as a positive control of the stimulation of the HK macrophages mimicking a pathogen infection." (PMID 38099984, 2024). "Considering the expression of IL-10 by MDSCs recruited to the lungs of infected mice, the only difference observed between WT and TLR4KO animals was a lower frequency of IL-10+ M-MDSCs in TLR4-deficient mice after 72 hours of infection." (PMID 39035356, 2024). "A prior study showed that neutralization of TLR2 and TLR4 on monocytes from patients with CL caused them to be less susceptible to in vitro infection and generate lower amounts of oxidants, upon incubation with L braziliensis." (PMID 38912968, 2024).
infection (continued). "The TLR4-NF-κB pathway is a classic inflammatory pathway activated after infection with S. aureus and it can cause an inflammatory response." (PMID 38525077, 2024). "In pathogenic infections, TLR4 activation is closely associated with inflammation, autophagy, and nitrogen oxidative stress." (PMID 38504994, 2024). "TLR4 is a pattern recognition receptor that plays an important role in modulating immune response, and deficiency of TLR4 leads to decreased inflammation, increasing infection, and impaired reepithelialization in skin wounds in mice." (PMID 38317065, 2024). "While IRE1α, XBP1, and TLR4 KO macrophages all showed reduced glycolysis during infection, only the IRE1α-deficient macrophages showed a reduced bacterial burden, suggesting that IRE1α supports B. abortus replication independently of enhanced glycolysis." (PMID 36475773, 2023). "Secreted GP has also been shown to trigger a TLR4-dependent cascade, rendering target cells more susceptible to subsequent infection by EBOV." (PMID 38035334, 2023). "Surprisingly, in this study, we observed that pregnant mice deficient for both TLR2 and TLR4 (TLR2/4) were able to curtail the ascending infection of a hyaluronidase-proficient WT GBS strain." (PMID 37747229, 2023). "TLR4 activation results in increased ACE2 expression on the cellular surface of circulating monocytes leading to increased susceptibility to infection with SARS-CoV-2." (PMID 36776845, 2023). "We postulate that the chronic, non-infectious inflammation induces a negative feedback loop within the inflammatory cascade, and the suppressed expression of TLR4 renders the mice more susceptible to infections." (PMID 38203647, 2023). "have a modified LPS that is a weak TLR4 agonist and encode an effector that downregulates TLR4 signaling during infection, TLR4 has been shown to play a role in the response to Brucella infection." (PMID 36475773, 2023). "Of greater significance, however, is the fact that TLR4-mediated oxidative stress, innate immune responses, and autophagy exhibit a dual role in combating pathogenic infections." (PMID 37443803, 2023). "In TLR4-deficient mice, the recruitment into the lungs and cytotoxic activity of NK cells was diminished upon infection compared to wild-type mice, indicating that RSV F protein activation of TLR4 is important for the recruitment and activity of NK cells." (PMID 37896776, 2023). "Mice with TLR4 deficiency had increased survival from lethal infection of influenza virus and the administration of TLR4 antagonist eritoran reduced viral titers and cytokine expression and improved pulmonary pathological changes and pulmonary function." (PMID 37089926, 2023). "Our laboratory engineered a knock-in mouse strain that homozygously expresses homologous SNPs (D298G/N397I) in murine TLR4, and this model displays similar LPS-hyporesponsiveness and altered susceptibility to infection as previously reported in human studies." (PMID 37768050, 2023). "This study reports the role of SCARB1 in infection and its potential association in TLR4 signaling on bacterial challenge in Goat mammary epithelial cells (GMECs)." (PMID 36604713, 2023). "Because TLR4 and NF-κB/AP-1 signaling cascades play major roles in inflammatory responses caused by the infection of PAMPs such as LPS, regulating TLR4 and NF-κB/AP-1 is an attractive target for both acute and chronic inflammatory diseases." (PMID 37111237, 2023). "CD36 can associate with TLR2/6 or TLR4/6 complexes and favor immune response in context of infection or sterile inflammation." (PMID 37996952, 2023). "In a biliary model of cryptosporidiosis, infections in TLR4 deficient mice were more severe and unresolving compared to controls." (PMID 37325809, 2023). "Although single-PEDV infection showed up-regulation on cell-membrane- (TLR4) and endosomal-associated (TLR3 and TLR8) TLRs by 5 DPI, it seems that these TLRs did exert a sufficient modulatory effect on MyD88 and TRIF." (PMID 36376395, 2022).
infection (continued). "One of the most studied innate immunity polymorphisms is the TLR4 Asp299Gly (rs4986790) polymorphism, which interferes with TLR4 signal transduction; thus, it is supposed to affect host susceptibility to infections and microbial invasions." (PMID 36142893, 2022). "Oral administration of this dendrimer significantly lowered the level of pro-inflammatory cytokines in rhesus macaques, demonstrating the potential of nano-assisted TLR4 antagonist for controlled resolution of infection-associated inflammation." (PMID 35986268, 2022). "There was a statistically significant association between the TLR4 polymorphism (rs4986790) and infection with Acinetobacter baumannii (p = 0.001) and infection with undetermined Gram (−) bacilli." (PMID 36142893, 2022). "While a consensus has not been made on which SARS-CoV-2 proteins activate which surface TLRs, several studies suggest that SARS-CoV-2 proteins contribute to detrimental cytokine storm via TLR2 or TLR4 associated with severe disease during infection." (PMID 36680092, 2022). "In step 4) TLR4 levels cause the expression of pro-inflammatory cytokines and the maturation of APCs of the innate immune system that will define the course of the infection." (PMID 36506333, 2022). "Coherently, TMUV infection of susceptible cells was inhibited by an anti-TLR4 antibody, purified soluble TLR4 protein, and knockdown of TLR4 expression." (PMID 36379254, 2022). "Developing infection with Acinetobacter baumannii was found to have a statistically significant association with the TLR4 polymorphism (p = 0.001)." (PMID 36142893, 2022). "TLR4-deficient mice are more susceptible to infection than control mice and have higher bacterial loads." (PMID 33966642, 2021). "Yet, when fucoidan was applied in the pretreatment setting, it was also shown to potentiate the NF-κB axis to reduce susceptibility to infection via scavenger receptor A and TLR4 activation in an antibiotic-like fashion." (PMID 34444774, 2021). "It is likely that the distribution of TLR4 gene polymorphisms has ethnic differences due to local evolutionary pressures by infection." (PMID 33777838, 2021). "Activation of TLR4 is closely related to inflammation, autophagy, and nitroxidative stress during a pathogenic infection." (PMID 34746034, 2021). "The expression of TLR4 on alveolar epithelial cells type II, e.g., A549 cells, that are in charge for alveolar damage repair during infection and tissue injury is a fundamental hallmark for cell regeneration (self-renewal) and wound repair mechanisms." (PMID 33429882, 2021). "Increased TLR-4 is associated with an enhanced gastroepithelial barrier, which provides defense against pathogen invasion and infection." (PMID 34527718, 2021). "In TLR4-deficient mice, significantly less LPS was deacylated at the site of infection than in wild-type littermates." (PMID 33057840, 2021). "TLR4/5 has been identified in catfish to function as acute innate immune markers and shows an increased level in response to infection with pathogenic bacteria." (PMID 34561532, 2021). "Several studies have previously demonstrated low parasitic load and resistance to infection in TLR2- or TLR4-deficient experimental animal models." (PMID 34691019, 2021). "This phenomenon can be explained, at least partly, by the genetic polymorphism of interleukin 1-beta, TLR-4 (Toll-like receptor 4) signalling and/or variations in a patient’s age at the time of infection acquisition." (PMID 34944861, 2021). "In this review, we discuss recent studies on the activities of TLR4, autophagy, and nitroxidative stress during pathogenic microorganism infections, with a particular focus on the mechanisms of TLR4-mediated autophagy and nitroxidative stress." (PMID 34746034, 2021). "Among the L. pneumophila-induced cytokines impacted by TLR3 and/or TLR4, IL-6 and IL-1β are associated with increased neutrophil infiltration to sites of infection." (PMID 34280250, 2021).
infection (continued). "In this study, after exposing bMECs to K. pneumoniae, mRNA levels of TLR4 and NF-κB, in the pathway of regulating inflammatory response in bMECs, were significantly up-regulated and positively associated with duration of infection." (PMID 33468111, 2021). "In contrast, TLR4-deficient BALB/c mice were susceptible to infection with P. aeruginosa and when compared to wild type controls, exhibited increased corneal opacity, PMN infiltration, viable bacterial load, and perforated corneas." (PMID 34684184, 2021). "After infection, TLR4-deficient mice also showed increased mRNA expression of proinflammatory cytokines IL-1α and CXCL2 and type-1–associated cytokines interferon [(IFN)-γ and IL-18] when compared with wild type BALB/c mice." (PMID 34684184, 2021). "During infection, either reduced Neu1 or enhanced siglec-E-TLR4 association ubiquitinates and degrades TLR4." (PMID 33763070, 2021). "In the preemptive group, we found associations with infections for TLR4 rs11536889 (p = 0.0082, OR 0.194, 95% CI 0.055–0.693) and with rejection for IFN-γ rs2069707 (p = 0.201, 95% OR 0.039–1.035)." (PMID 33861738, 2021). "TLR4 has been applied as a target for immunopharmacological control of infection from pathogenic bacteria and even viruses." (PMID 33291425, 2020). "BMDMs differentiated from TLR4-deficient mutant mice produced more IL-10 after Mtb strain HN878 infection than after H37Rv infection." (PMID 32403973, 2020). "Transcriptome group 1 (CAMP, CD14, FN1, TREM1) encodes for proteins that relate to acute response to infection, in particular to the LPS/TLR4 signaling pathway." (PMID 32325790, 2020). "Herein; we investigated the impact of the TLR2 and TLR4 polymorphisms on the susceptibility of AML patients to infection as well as patient’s outcome." (PMID 33247673, 2020). "They found that wild-type (WT) mice expressing competent TLR4 receptors in their immune cells are resistant to lethal infection with L. interrogans whereas TLR4 knockouts are susceptible, have larger numbers of Leptospira in tissues and succumb to infection." (PMID 33519799, 2020). "This study aimed to investigate the association between TLR2 and TLR4 polymorphism and the risk of acquiring severe infections, and impact on AML patient’s outcome." (PMID 33247673, 2020). "TLR4 is an important ligand to lipopolysaccharide (LPS) of gram-negative bacteria and plays an important central role in recognizing pathogenic infection." (PMID 32362888, 2020). "Parasitic infection caused by Plasmodium is known to stimulate various immune cells by activation of the TLR4–NF-κB axis." (PMID 32508811, 2020). "Mice in general are asymptomatic reservoirs, however studies have shown that young mice from C3H/HeJ strain, deficient to Toll-like receptor 4 (TLR4), are susceptible to infection by Leptospira and represent an ideal model for immune response studies." (PMID 30616505, 2019). "Previously, the TLR4 expressions in peripheral blood mononuclear cells were shown an association between drug treatment and clinical outcomes of infection." (PMID 30765614, 2019). "This novel finding establishes a link between enhanced α2,3-linked sialic acids on TLR4 and reduced membrane-bound Neu1 which plays a significant role for inhibiting downstream signaling to establish successful infection in the host cells." (PMID 31649671, 2019). "Remarkably, wild-type mice survived asymptomatically with pbgA-lpxC salmonellae in their livers and spleens for months, but Toll-like receptor 4-deficient animals succumbed to these infections within roughly 1 week." (PMID 31611279, 2019). "The acute injury caused by LPS infection over 12 h was mainly an inflammatory reaction and clearly the response of the TLR4-NFκB pathway." (PMID 31446815, 2019).